NTF3 (neurotrophin 3)
Diseases named in the same sentence as NTF3 in open-access papers (continued):
Sharing a sentence is not in itself a finding about the gene and the disease.
neuropathic pain (1 paper, 2021). Chronic pain caused by damage to nerve fibers. "In the CCI model of neuropathic pain, Ntf3 is capable of attenuating expression of Nav1.9 mRNA and protein, indicating a possible ability of Ntf3 modulating the plasticity of ribbon synapse via Nav1.9 in cochlea." (PMID 33752606, 2021).
osteoarthritis (1 paper, 2024). A noninflammatory degenerative joint disease occurring chiefly in older persons, characterized by degeneration of the articular cartilage, hypertrophy of bone at the margins and changes in the synovial membrane. "Among the DMRs annotated in genes, MCF2L, which regulates neurotrophin-3 induced cell migration, is associated with inflammatory processes and osteoarthritis." (PMID 39020437, 2024).
osteoporosis (1 paper, 2022). A condition of reduced bone mass, with decreased cortical thickness and a decrease in the number and size of the trabeculae of cancellous bone (but normal chemical composition), resulting in increased fracture incidence. "And in our study, for the first time, the intimate association of the other 3 miRNAs (hsa-miR-18b-3p and hsa-miR-519e-5p) and 4 genes (IFNAR2, ARHGAP5, FLNC, and NTF3) with osteoporosis was discovered." (PMID 35757478, 2022). "After construction the miRNA-gene interaction network, we identified 6 hub miRNAs (hsa-miR-18b-3p, hsa-miR-361-3p, hsa-miR-484, hsa-miR-519e-5p, hsa-miR-940, and hsa-miR-1275) and 6 hub genes (THBS1, IFNAR2, ARHGAP5, TUBB2B, FLNC, and NTF3) for osteoporosis." (PMID 35757478, 2022).
pituitary adenomas (1 paper, 2025). "Further, an increased expression of neurotrophin 3 has been found in GH-secreting pituitary adenomas and has been hypothesized to be involved in pituitary tumour growth and progression." (PMID 41071261, 2025).
primitive neuroectodermal brain tumors (1 paper, 2022). "In primitive neuroectodermal brain tumors (PNETS), TrkC accelerates apoptosis and terminal neuronal differentiation through its ligand NTF3 14,15." (PMID 36263167, 2022). "In primitive neuroectodermal brain tumors (PNETS), TrkC accelerates apoptosis and terminal neuronal differentiation via its ligand NTF3 14,15." (PMID 36263167, 2022).
proliferative diabetic retinopathy (1 paper, 2013). Advanced retinopathy due to diabetes mellitus characterized by the formation of new vessels in the retina. "We investigated the expression of the NTs nerve growth factor (NGF), brain-derived neurotrophic factor (BDNF), neurotrophin-3 (NT-3), and neurotrophin-4 (NT-4) and their receptors TrkA, TrkB, and TrkC in proliferative diabetic retinopathy (PDR)." (PMID 23762379, 2013).
sarcoidosis (1 paper, 2025). Sarcoidosis is a multisystemic disorder of unknown cause characterized by the formation of immune granulomas in involved organs. "BALF concentrations of NGF and neurotrophin-3 (NT-3) were significantly increased, and immunoreactivity against NGF, BDNF, NT-3, and tyrosine protein kinase receptors (TrkA, TrkB, and TrkC) in granulomas was found in patients with sarcoidosis using immunohistochemical analysis." (PMID 40361957, 2025).
scoliosis (1 paper, 2025). A congenital or acquired spinal deformity characterized by lateral curvature of the spine. "Tryptophan hydroxylase (TPH1 rs10488682), insulin-like growth factor (IGF1 rs5742612), neurotrophin 3 (NTF3 gene promoter at rs11063714), interleukin-17 receptor C (IL17RC rs708567), melatonin receptor 1B (MTNR1B rs4753426) were identified as risk factors for scoliosis curve progression." (PMID 39781499, 2025).
Tinnitus (1 paper, 2024). Tinnitus is an auditory perception that can be described as the experience of sound, in the ear or in the head, in the absence of external acoustic stimulation. "Remarkably, the growth factors NGF, NTF3, and FGF2 are only present in the pathways associated with tinnitus." (PMID 39062188, 2024). "The in-depth analysis of the targets of NTRK3/NTRK1/NTF3 under physiological and tinnitus conditions could help to create new starting points for therapeutic considerations." (PMID 39062188, 2024). "In tinnitus, the predominant activity is that of other proteins, namely, the top key proteins BDNF/NTRK3/NTRK1/NTF3 in interaction with a number of Top2 key proteins, all members of the IEGs." (PMID 39062188, 2024). "The key proteins NTRK3, NTRK1, and NTF3 in tinnitus are not simply involved in activating or inhibiting processes but in remodeling of synaptic transmission processes." (PMID 39062188, 2024).
triple-negative breast carcinoma (1 paper, 2012). An invasive breast carcinoma which is negative for expression of estrogen receptor (ER), progesterone receptor (PR), and human epidermal growth factor receptor 2 (HER2). "Thus, NF-κB transcriptionally up-regulates TrkB and NTF3 through direct binding of RelA and NF-κB1 to the regions in the promoters, and this increased transcription is necessary and sufficient for triple negative breast cancer cells to resist anoikis." (PMID 23185507, 2012).
viral encephalitis (1 paper, 2024). Encephalitis resulting from viral infection. "155-2.219, p = 0.005) and neurotrophin-3 levels (OR=1.945; 95% CI=1.236-3.061, p = 0.004) were positively associated with the development of viral encephalitis." (PMID 40008261, 2024). "The results suggest that the inflammatory factors with a potential causal relationship with viral encephalitis are artemin, C-C motif chemokine 28, C-X-C motif chemokine 1, interleukin-10 and neurotrophin-3." (PMID 40008261, 2024).
tumor (17 papers, 2016 to 2025). "Specifically, we observed a loss of loops in the NTF3 gene region in tumour, accompanied by a significant downregulation of the NTF3 expression compared to normal tissue." (PMID 38769659, 2024). "The KM website and our center clinical data have proved that the low NTF3 expression was associated with poor prognosis and is significantly correlated with the tumor size, staging, and grading." (PMID 36263167, 2022). "To further clarify the relationship between expression of NTF3 and different immune cells, we analyzed the association of NTF3 expression with 28 kinds of tumor-infiltrating lymphocytes (TILs) in TISIDB by conducting Spearman correlation analysis." (PMID 34938753, 2021). "Further analysis found that NTF3 was associated with tumor immunity." (PMID 34938753, 2021). "NGF and neurotrophin 3 (NT-3) are highly expressed in tumor-adjacent tissues in the brain, suggesting brain organotropism between the CD271-positive cells and the brain tumor niche." (PMID 40076927, 2025). "We investigated the genes associated with lost loops in the MAPK pathway and found that the NTF3 gene lost loops in somatotroph tumours and was downregulated in tumour." (PMID 38769659, 2024). "The different expression in tumor cells from different organ systems further complicates the understanding of the role of NTF-3 and MYBL1 in tumorigenesis." (PMID 39408891, 2024). "The most notable differences in gene expression associated with miRNA-221 between non-tumor hepatocytes and viral-induced HCC involved NTF-3 and MYBL1 genes." (PMID 39408891, 2024). "The results indicated that CD320, PSMD14, and SORT1 protein levels were higher in tumor tissues than in normal tissues, while the level of NTF3 in the normal tissues was higher than that in the tumor tissues." (PMID 36959615, 2023). "Considering NTF3 acts as a tumor-suppressor gene, the most common way to regulate tumor suppressor genes is epigenetics, which is divided into 3 categories: histone methylation, DNA methylation, and histone acetylation." (PMID 36263167, 2022). "In summary, we have found that NTF3 is an anti-tumor protein that inhibits tumor proliferation, invasion, and migration through the apoptotic pathway." (PMID 36263167, 2022). "It is suggested that NTF3 affects tumor progression by regulating cell metabolism, proliferation, invasion, and metastasis." (PMID 34938753, 2021). "Together, these results reveal that NTF3 participates in the tumor immune microenvironment by regulating T cells in HCC." (PMID 34938753, 2021). "This study is the first bioinformatic analysis to explore the relationship between NTF3 and tumor immunity in HCC." (PMID 34938753, 2021). "As a new tumor suppressor, NTF3 is a member of the neurotrophic family of ligands." (PMID 36263167, 2022). "In vivo experiments further verified that NTF3 is a tumor suppressor." (PMID 36263167, 2022). "In addition, we analyzed the relationship between NTF3 and various immune infiltrating cells in the tumor microenvironment." (PMID 34938753, 2021). "Collectively, the enrichment analysis revealed some potential mechanisms of NTF3 in tumor progression, proved the reliability of NTF3 as a prognostic factor, and suggested that NTF3 may be a potential target for HCC therapy." (PMID 34938753, 2021). "Moreover, neurotrophin-3 expression, regulated via eccDNA, has been found to limit the phagocytic capabilities of microglia and deactivate the immune response within the brain, consequently impacting the effectiveness of tumor immunotherapy." (PMID 39534571, 2023). "In brief, NGF, the Brain-Derived Neurotrophic Factor (BDNF), Neutrophin 3 (NTF3) and Neutrophin 4 (NTF4) are the major neurotransmitters secreted by neural and tumour cells in PDAC." (PMID 36497277, 2022). "CIBERSORT analysis indicated that NTF3 expression was positively correlated with CD4+ cells, mast cells, NK cells, macrophages and B cells in the tumor microenvironment." (PMID 34938753, 2021).
tumor (continued). "NTF-3 was considered to have significantly lower expression in HCC tissue than in non-tumor hepatocytes, while the MYBL1 gene was observed to be significantly overexpressed in tumor tissue when compared with non-tumor hepatocytes using in silico analysis." (PMID 39408891, 2024). "Interestingly, when we evaluated the possible correlation between NTF-3 and MYBL1 gene expression in tissue samples from patients with HCC of viral origin, cirrhotic tissue, and non-tumor liver tissue, we found a positive correlation only in the HCC group." (PMID 39408891, 2024). "The mechanisms leading to the upregulated NTF-3 and MYBL1 expression in tumor tissue of one organ or downregulated expression in tumor tissue of another organ are still unknown." (PMID 39408891, 2024). "When compared with the weight of the control group, that of the BALB/c nude mice did not change significantly, albeit the tumor weight and volume of the NTF3 overexpressing group had significantly reduced." (PMID 36263167, 2022). "Chemoattractants are mediators secreted by tumor cells, such as vascular endothelial growth factor (VEGF) and transforming growth factor (TGF) β1, as well as the cytokines interleukin (IL)-8 and neurotrophin-3 (NT-3), which attract MSCs to the tumor microenvironment (TME)." (PMID 35741334, 2022). "Hence, understanding the interplay between NTF-3-mediated signaling and MYBL1 activity could provide insights into their collective impact on tumor development and progression." (PMID 39408891, 2024). "As NTF-3 is known to regulate the PI3K/AKT signaling pathway by binding directly to the TrkC receptor, it is evident that it might have a role in the development of different malignant tumors, but also that its aberrations could be different depending on the type of tumor." (PMID 39408891, 2024). "Contrary to our in silico results, we did not observe a statistical difference in NTF-3 expression between patients’ samples of HCC tissue of alcohol etiology, cirrhotic tissue, and non-tumor hepatocytes." (PMID 39408891, 2024).
cancer (12 papers, 2010 to 2024). A tumor composed of atypical neoplastic, often pleomorphic cells that invade other tissues. "Functional network analysis revealed that NTF3 regulates HCC progression through a variety of cancer-related kinases, transcription factors and signaling pathways." (PMID 34938753, 2021). "A previous study showed that nerve growth factor (NGF) family members such as NGF, neurotrophin-3, and neurotrophin-4/5, which are other ligands of TrkB, influence cancer proliferation." (PMID 28423707, 2017). "Thus, we investigated the potential influence of NTF3 expression on cancer immunotherapy and found a positive correlation between NTF3 expression and immune checkpoints, including PD-L1, TIGIT, and TIM-3, but not CTLA4." (PMID 34938753, 2021). "Neurotrophins (Nerve Growth Factor (NGF), Brain-Derived Neurotrophic Factor (BDNF), and Neurotrophin-3 (NT-3)), as well as their cell surface receptors (p75, TrkA, TrkB, and TrkC) are validated targets for therapeutics in a variety of pathologies ranging from cancer to neurodegeneration." (PMID 24603864, 2014). "We also noticed that growth factors, including NOV, BMP4, MDK, GDF15, VEGFC, NTF3, and LIF, were previously reported to promote cancer development, especially in cancer metastasis in various cancers, including CRC." (PMID 34440086, 2021). "For promoter-associated CpG islands, a number of them, including those of NTF3, FGF, OSR1, HOXA6, NPY and WT1, have previously been reported as differentially methylated in other cancer types." (PMID 20051947, 2010).
brain disease (1 paper, 2023). "In a study by Requena-Ocaña and colleagues, BDNF and neurotrophin-3 concentrations were related to the cognitive reserve and the individual’s ability to manage a brain disease through compensatory mechanisms of cognitive stimulation." (PMID 37509436, 2023).
infection (1 paper, 2024). The state of being infected such as from the introduction of a foreign agent such as serum, vaccine, antigenic substance or organism. "After 28 days of infection, NTF3 expression in these regions was significantly altered at both mRNA and protein levels, and the optimal shRNA sequence (AAV‐shRNA1) was identified." (PMID 39690816, 2024).
peripheral neuropathies (1 paper, 2017). "The effect of neurotrophin-3 administration on myelination and on the peripheral neuropathies needs further investigation before in can be translated to the clinic." (PMID 27957719, 2017).
NTF3 also shares sentences with these, for which no sentence is quoted: eating disorder (3 papers); Alzheimer disease (2); colorectal cancer (2); Hearing impairment (2); neurologic disease (2); Obesity (2); age-related hearing loss (1); alcohol use disorder (1); allergic rhinitis (1); allergies (1); Ataxia (1); atherosclerosis (1); atopic dermatitis (1); B-cell lymphoma (1); Charcot Marie Tooth neuropathy (1); cognitive disorder (1); colitis (1); colon cancer (1); delirium (1); demyelination (1); embryonic carcinoma (1); epilepsy (1); esophageal squamous cell carcinoma (1); fibrosis (1); galactosemia (1); gastric cancer (1); Hydrocephalus (1); hypertensive encephalopathy (1); injury (1); lung squamous cell carcinoma (1).
A further 20 diseases each share a sentence with NTF3 in 1 paper.